IDO1 (indoleamine 2,3-dioxygenase 1)
Diseases named in the same sentence as IDO1 in open-access papers (continued):
Sharing a sentence is not in itself a finding about the gene and the disease.
diabetes (29 papers, 2014 to 2026). "The administration of a proteasome inhibitor—bortezomib—to prediabetic NOD mice caused the prevention of diabetes onset through a mechanism related to restoration of IDO1 expression in pDCs from these animals and reinstallation immune tolerance to pancreatic autoantigen." (PMID 34576041, 2021). "Preventing diabetes might be a pathway by which IDO1 lowers the risk of IHD." (PMID 31186442, 2019). "Among these enzymes, IDO1 serves as an immunomodulator and plays a significant role in diabetes and liver disease." (PMID 37305057, 2023). "This study evaluated the effect of endurance training (EndTr) and nettle leaf extract (NLE) on the IDO1-KYN-AHR pathway in the livers of rats with streptozotocin-induced diabetes." (PMID 37305057, 2023). "This study aimed to assess the effects of EndTr, NLE, and their combination on the IDO1-KYN-AHR pathway in the liver of rats with STZ-induced diabetes while taking into account the increasing incidence of T1D worldwide." (PMID 37305057, 2023). "Ido1−/− mice demonstrated that the protective effect of tocilizumab on diabetes development was dependent on IDO1, highlighting possible therapeutic implications." (PMID 35455658, 2022). "Significant attention has been paid to the immunoregulatory role of IDO1 in the most prevalent, organ-specific autoimmune endocrinopathies—type 1 diabetes mellitus (T1DM) and autoimmune thyroiditis." (PMID 34576041, 2021). "The protective role of IDO1 in the development of autoimmune diabetes was also confirmed in a streptozocin-induced model of diabetes." (PMID 34576041, 2021). "This study suggests that IFN-γ, the strong activator of IDO1 expression, can play a protective or deleterious role in diabetes development." (PMID 34576041, 2021). "Compared to TLR-induced cytokine/chemokine secretion, the expression of immunomodulatory effectors like Cox-2, HO-1, and IDO-1 is poorly studied in filariasis and diabetes." (PMID 34566972, 2021). "Unexpectedly, both IDO1 and KAT3 were inversely associated with type 2 diabetes, suggesting the kynurenine pathway also plays a role in development of diabetes." (PMID 31186442, 2019). "Previous studies of IDO1 and type 2 diabetes are limited, although some have suggested diabetes up-regulates the tryptophan-kynurenine pathway." (PMID 31186442, 2019). "When administered in vivo to prediabetic mice, the drug prevented diabetes onset through IDO1- and pDC-dependent mechanisms." (PMID 28450863, 2017). "Here, we report that BTZ confers tolerogenic effects on pDCs from NOD mice, resulting in enhanced generation of regulatory T cells and preventing diabetes onset in mice through an IDO1-dependent mechanism." (PMID 28450863, 2017). "Interestingly, circulating tryptophan is inversely associated with diabetes and CRC because the inhibition of indoleamine 2,3-dioxygenase 1 (IDO1) increases antitumour immunity." (PMID 40457130, 2025). "This study concluded that EndTr and NLE may have synergistic effects in reestablishing the homeostasis of the IDO1-KYN-AHR pathway in the liver of rats with diabetes." (PMID 37305057, 2023). "The higher activity of IDO-1 (KTR) is well-documented in obese subjects and patients with cardiac events, and it is positively associated with inflammation, but the association between KTR and diabetes is less clear." (PMID 35736425, 2022). "The IDO1 protein showed inverse association with ischemic heart disease, with its risk factor, diabetes mellitus type 2, but it was not clearly associated with systolic or diastolic blood pressure." (PMID 35211110, 2021). "However, we caution that an important follow up study should be undertaken to directly confirm an increase in IDO1 activity and mRNA levels in peripheral blood mononuclear cells from diabetics with neuropathic pain." (PMID 32973438, 2020).
diabetes (continued). "Moreover, the proinflammatory cytokine, IFN-γ can modulate the activity of rate-limiting enzyme of KP, the IDO1, therefore the dysregulation of the KP might be involved in the pathogenesis of CAD and/or its risk factors, including diabetes mellitus." (PMID 35211110, 2021). "In addition, small subsets of genes encoding for regulatory factors and enzymatic processes that have been implicated in the pathogenesis of type 2 diabetes mellitus (T2DM) were profiled, including interferon regulatory factors (IRF), indoleamine 2,3-dioxygenase (IDO1) and kynureninase (KYNU)." (PMID 29746559, 2018). "Recently, the IDO1-KYN-AHR pathway has been recognized as a promising therapeutic target for a variety of diseases, including cancer and diabetes." (PMID 37305057, 2023). "Positive correlation of increased IDO1 activity and KYN with incidence of CAD and low-grade inflammation, obesity, dyslipidemia, insulin resistance, diabetes and metabolic syndrome were also demonstrated." (PMID 35211110, 2021). "Mice protected from diabetes by BTZ in vivo also displayed increased percentages of Foxp3+CD4+ and IDO1 protein expression in both pLNs and pancreata, and an increased systemic Kyn/Trp ratio." (PMID 28450863, 2017). "The significance of three-way interaction of exercise, NLE, and diabetes means that the interaction among the two factors (exercise × NLE) is different across the levels of the third factor (diabetes) for AHR, CYP1A1, KYN, IDO1, and MDA." (PMID 37305057, 2023). "Given the complex function of IDO1 and wide consumption of the essential amino acid tryptophan in our diets, IDO1 could be a potential target for IHD, diabetes and prostate cancer prevention worthy of further investigation." (PMID 31186442, 2019). "Consequently, the IDO1-KYN-AHR pathway may have the potential to exert a profound influence on the pathophysiology of liver and diabetes." (PMID 37305057, 2023). "IDO1 might be a potential therapeutic target for IHD, diabetes and prostate cancer." (PMID 31186442, 2019).
leukemia (29 papers, 2011 to 2025). A malignant (clonal) hematologic disorder, involving hematopoietic stem cells and characterized by the presence of primitive or atypical myeloid or lymphoid cells in the bone marrow and the blood. "Additionally, ATP release from chemotherapy-treated leukemia cells is shown to induce IDO-1, causing increases in Tregs and tolerogenic dendritic cells that can limit response to immune checkpoint blockade." (PMID 35011741, 2022). "The treatment with IDO1 inhibitors restored the elevated levels of leukemia blast cells and lower levels of red blood cells and mature neutrophils in AML model mice to the levels similar to non-AML." (PMID 40234305, 2025). "It is likely that As-A inhibits leukemia in part through suppression of the immune checkpoint modulators IDO1 and TDO2." (PMID 39769192, 2024). "SAA acts with a mechanism of positive feedback on leukemia cells by increasing the expression of indoleamine 2,3-dioxygenase-1 (IDO1), the rate-limiting enzyme for Kyn synthesis, thereby enabling AML progression." (PMID 37234820, 2023). "Firstly, we analyzed effects of the IDO1 modulator 1-methyl-D-tryptophan (1MT) on tumor cell engraftment and leukemia development, whereby we started to treat the mice with 1MT on the same day they were transplanted with the tumor cells." (PMID 33920868, 2021). "We further explored induction of IDO1 expression after adoptive transfer of TCL1 leukemia (TCL1 AT) in syngeneic WT mice and observed a higher frequency of IDO1-expressing monocytes and neutrophils in these mice compared to WT controls." (PMID 33920868, 2021). "In sum, modulation of IDO1 activity with 1MT resulted in only transient effects on leukemia development in TCL1 AT mice." (PMID 33920868, 2021). "Our data show that leukemia development in the TCL1 mouse model of CLL is associated with higher expression and activity of the Trp-degrading enzyme IDO1." (PMID 33920868, 2021). "The expression of indoleamine 2,3-dioxygenase-1 (IDO1) by leukemia cells was for instance correlated with unfavorable prognosis in childhood AML." (PMID 32158444, 2020). "This is supported by the clinical observation that higher levels of IDO1 expression by leukemia cells correlates with an adverse prognosis in childhood AML." (PMID 31881776, 2019). "The most known suppressive mechanism in AML is the up-regulation of IDO1 expression on leukemia cells." (PMID 31649875, 2019). "These DCs are in vitro fully competent at inducing through IDO1 a population of Tregs, which in turn inhibit leukemia-specific T-cell immune response." (PMID 29312358, 2017). "DCs cultured with daunorubicin-treated AML cells upregulated indoleamine 2,3-dioxygenase 1 (IDO1), which induced anti-leukemia Tregs." (PMID 29312358, 2017). "Taken together, these in vivo results demonstrate that ATP release from DNR-treated dying leukemia cells has a role in the induction of an immune suppressive microenvironment, which comprises Tregs and IDO1-expressing DCs." (PMID 29312358, 2017). "To better elucidate the effects of PGE2 in the setting of dendritic cell vaccination after chemotherapy-induced remission in acute myeloid leukemia, we evaluated IDO1 expression in normal Mo-DCs obtained from leukemia patients in complete remission." (PMID 25815345, 2015). "Overall, these findings show that the expression of IDO1 in DCs matured in presence of PGE2 is able to inhibit the generation of both leukemia-reactive IFN-γ-secreting CD4+ and CD8+ T cells." (PMID 25815345, 2015). "Herein, we provide evidence that IDO1 is induced in leukemia cells by IFN-γ in around half of children with AML in a signal transducer and activator of transcription 3 (STAT3)-dependent manner." (PMID 24903009, 2014). "We initially evaluated IDO1 protein levels in leukemia blasts that were either maintained in culture medium alone or were challenged with IFN-γ for 72 hours." (PMID 24903009, 2014).
leukemia (continued). "Given the undisputed role of IDO1 in activating and stabilizing Treg cells, we measured intracellular FoxP3 levels after culturing allogeneic naïve T cells with IDO-expressing leukemia blasts." (PMID 24903009, 2014). "Our findings thus portend favourable implications for immunotherapy trials aimed at reinstituting anti-leukaemia immune responses through the inhibition of the COX-2/IDO1 axis." (PMID 23973990, 2013). "Thus, leukemia cells can negatively regulate T cell function by up-regulating the expression of IDO1." (PMID 31881776, 2019). "With a median follow-up of 37.4 months (range 3-80), the 8-year EFS of children whose leukemia blasts up-regulated IDO1 in response to IFN-γ was equal to 16.4% (SE 9.8), compared with 48.0% (SE 12.1) in children whose AML blasts were unresponsive to IFN-γ (p=0.035)." (PMID 24903009, 2014). "The present study suggests that the regulation of IDO1 expression by inhibition of the COX-2/PGE2 pathway may constrain the leukaemia-induced immune suppression." (PMID 23973990, 2013). "It is presently unknown whether IFN-γ-induced COX-2 may also regulate IDO1 expression in human leukaemia cells." (PMID 23973990, 2013). "CLL is associated with an increased IDO1 expression and activity, but its pharmaceutical inhibition is not sufficient to control leukemia development in a mouse model of CLL, suggesting compensatory mechanisms, such as that of IL4I1, in place that maintain immunosuppression." (PMID 33920868, 2021). "In conclusion, our findings could constitute a definitive proof of the relation, occurring in leukemia microenvironment, between IDO1 induction on AML blasts mediated by NK cell-produced IFNγ and the consequent functional deregulation of NK cells that favors AML immune escape." (PMID 25886742, 2015). "The results indicated that KYN significantly increased cell proliferation marker expression (cyclin D1, E2F1, and Ki-67), as well as IDO1, TDO2, Ikaros1, AML1, and ETV6 expression, in leukemia cells." (PMID 35687267, 2023). "IDO1-expressing AML blasts consequently down-regulate NK cell degranulation activity, by sustaining leukemia immune escape." (PMID 25886742, 2015). "Accordingly, blocking IDO1 activity by 1-MT-L in AML-loaded DCs, matured in presence of PGE2 (and consequently expressing high level of IDO1), strongly enhanced the leukemia-specific IFN-γ production by T-cells." (PMID 25815345, 2015). "The addition of IFN-γ to leukemia blasts also translated into the up-regulation of phosphorylated STAT3, a phenomenon that was paralleled by the increase of IDO1 protein expression." (PMID 24903009, 2014). "Indeed, both IDO1 and TDO2 were identified as targets of As-A, leading to suppression of tryptophane-mediated Kyn production and leukemia suppression." (PMID 39769192, 2024). "Taken together, these data suggest that ATP release from DNR- and not ARA-C-treated leukemia cells is correlated with Tregs generation and IDO1 upregulation in mature DCs." (PMID 29312358, 2017). "Co-culture of NK cells with AML blasts resulted positive for IDO1 expression when compared with NK cells cultured in the absence of leukemia blasts." (PMID 25886742, 2015). "Through the construction of the CLL E-TCL1 mouse model, it was found that IDO1 and secretory IgM promote the expansion of MDSCs, but the inhibition of IDO1 could not reduce the recurrence of leukemia." (PMID 36978204, 2023). "To explore the potential of IDO1 as a therapeutic target for CLL, we treated mice after adoptive transfer of Eμ-TCL1 leukemia cells with the IDO1 modulator 1-methyl-D-tryptophan (1-MT) which resulted in a minor reduction in leukemia development which disappeared over time." (PMID 33920868, 2021). "In sum, despite the observed upregulation of IDO1 in CLL, its inhibition is not sufficient to control leukemia development in the Eμ-TCL1 adoptive transfer model." (PMID 33920868, 2021).
Anxiety (26 papers, 2010 to 2026). Intense feelings of nervousness, tension, or panic often arise in response to interpersonal stresses. "In our results, depressive- and anxiety-like behaviors were accompanied by the upregulation of IDO1 expression." (PMID 32116558, 2020). "In support of a major role of this enzyme in stress-induced disorders, preclinical studies have shown that IDO1-mediated activation of the KP by systemic immune challenges resulted in both anxiety and depressive-like symptoms in mice." (PMID 27828964, 2016). "Finally, in a preliminary study with a small sample size and mostly male patients, we demonstrate that patients undergoing surgery who suffer from increased anxiety, helplessness and social isolation show IDO1 activation." (PMID 20689575, 2010). "Our findings revealed that mice subjected to CMS exhibited anxiety- and depressive-like behaviors in the sucrose preference test, elevated plus maze, and forced swim test, along with increased interferon-γ, tumor necrosis factor-α, and indoleamine 2,3-dioxygenase-1 levels in the hippocampus." (PMID 30459574, 2018).
brain tumors (25 papers, 2012 to 2025). "Preclinically, tumor-derived IDO1 is essential for Treg accumulation and immunosuppression, since malignant brain tumors deficient for the enzyme result in spontaneous rejection mediated by a T-cell-dependent mechanism." (PMID 27057463, 2016). "IDO1 has been also implicated in the regulation of inflammation, as well as of T cell-mediated immune responses, in a variety of pathological conditions, including brain tumors." (PMID 27174915, 2016). "Blockade of IDO-1 using small molecule inhibitors in combination with immune checkpoint blockade induces prominent antitumor response in mouse models of brain tumors." (PMID 40475772, 2025). "Accumulating evidence highlight an important putative role for IDO1 in regulating tumor immunological escape in brain tumors." (PMID 36959545, 2023). "Another study also combined an oncolytic adenovirus carrying an activator of T cells with the IDO1 inhibitor for the treatment of brain tumors and achieve a promising therapeutic outcome via reshaping the antitumor immune responses." (PMID 37296221, 2023). "A non-metabolizable IDO1 substrate (α-methyl Trp, AMT) has been reported to target brain tumors with different profiles of IDO1 expression." (PMID 28159919, 2017). "Commensurate to the inflammatory signals (i.e. cytokines, chemokines, growth factors) that brain tumors induce, are potently immunosuppressive mechanisms that include the tryptophan catabolic enzyme, indoleamine 2,3 dioxygensase 1 (IDO1)." (PMID 27057463, 2016). "Wainwright and colleagues investigated the role of IDO1 in brain tumors and its impact on Treg recruitment and found that IDO1 expression increased recruitment of immunosuppressive Tregs that lead to tumor outgrowth." (PMID 26378585, 2015). "Indoleamine 2,3-dioxygenase 1 (IDO) is overexpressed in brain tumor and its critical involvement in regulating the levels of tumor-infiltrating Tregs is a major focus of this article." (PMID 24478778, 2014). "Using the appropriate immune checkpoint inhibitors in combination with IDO1 inhibitors might be an alternative treatment for both parenchymal and extra-parenchymal therapy resistant brain tumors." (PMID 35366268, 2021). "Within pediatric brain tumors, a phase I study of the oral IDO1 inhibitor, indoximod, identified a R2PD dose in pediatric patients with progressive high grade brain tumors and demonstrated safety when given concurrently with radiotherapy and temozolomide in newly diagnosed DIPG (NCT02502708)." (PMID 34277419, 2021). "Thus, IDO1 expression in brain tumor cells is likely to be triggered when IFNγ is produced from activated T cells and/or microglia and neurons." (PMID 32117235, 2020). "Thus, it will be interesting to determine whether co-inhibiting CTLA-4 and IDO1 lacks an additive/synergistic impact against brain tumors or if other undiscovered immunosuppressive mechanisms remain independent of the interaction." (PMID 27057463, 2016). "As IDO1 is overexpressed in glioma stem cells and as its expression can be induced by IFN-γ stimulation, its involvement in brain tumors and, accordingly, MB has also gained interest." (PMID 34771550, 2021). "IDO-1 expression has been shown in nine of ten human GBM biopsies and in brain tumor cell lines and GBM cell lines." (PMID 25415278, 2014). "Such IDO1-mediated TRP depletion from tissues alters inflammation, as well as T-cell mediated immune response, in a variety of pathological settings, including cancer and, in particular, brain tumors." (PMID 27174915, 2016). "More recently, genetic ablation of IDO1 alone was sufficient to phenocopy IDO‐inhibition with either D‐1MT or combined D- and L-1MT regarding important biomarkers of immune activation after chemo‐radiation therapy in a mouse brain tumor model." (PMID 26674411, 2015).